DKK1 (dickkopf Wnt signaling pathway inhibitor 1)
Diseases named in the same sentence as DKK1 in open-access papers (continued):
Sharing a sentence is not in itself a finding about the gene and the disease.
scrub typhus (1 paper, 2021). Scrub typhus is a rare dust mite-borne infectious disease caused by the Orientia tsutsugamushi bacterium and characterized clinically by an eruptive fever which is potentially serious. "We found i) Levels of SOST and in particular sFRP-3 and WIF-1 were markedly increased and DKK-1 decreased in scrub typhus patients at admission to the hospital compared to healthy controls." (PMID 33914733, 2021). "Notably, an opposite pattern was seen for DKK-1 that was decreased in patients with scrub typhus and in infectious controls compared to healthy individuals." (PMID 33914733, 2021). "DKK-1 and sFRP-3 displayed similar, but opposite, correlations with markers of monocyte/macrophage and endothelial cell activation in infectious controls and scrub typhus with negative associations for DKK1, and positive associations for sFRP-3." (PMID 33914733, 2021). "Herein we show that DKK-1 was negatively correlated with both markers of immune activation (i.e. sCD163 and sCD14) and vascular inflammation (i.e. VCAM1) in patients with scrub typhus and infectious controls suggesting a common mechanism." (PMID 33914733, 2021). "At recovery (median 17 days, range 5–135) after the initial sample, scrub typhus patients had a significant decrease in SOST and increase in DKK-1 levels compared to admission levels, reaching levels comparable to healthy controls." (PMID 33914733, 2021). "We hypothesized that plasma levels of the secreted Wnt modulators sFRP-3, DKK-1, SOST and WIF-1 would be regulated in scrub typhus and correlate with markers of inflammation and immune activation." (PMID 33914733, 2021).
soft tissue sarcoma (1 paper, 2021). A malignant neoplasm arising from muscle tissue, adipose tissue, blood vessels, fibrous tissue, or other supportive tissues excluding the bones. "Therefore, we identify DKK-1 as a pro-oncogenic protein in RMS and as a putative molecular target, which may have potential in the treatment of this soft tissue sarcoma." (PMID 34884726, 2021).
Solid Pseudopapillary Neoplasm of the Pancreas (1 paper, 2016). A low-grade malignant neoplasm that arises from the exocrine pancreas. "Eighteen cases of solid pseudopapillary neoplasms of the pancreas were evaluated for RNA expression levels of FLI1, DKK1, INPP5D (SHIP1), IGFBP3, PBK (TOPK), and BCL9 and BCL9L." (PMID 27539223, 2016).
sporotrichosis (1 paper, 2024). The commonest and least serious of the deep mycoses, characterized by nodular lesions of the cutaneous and subcutaneous tissues. "The results showed that compared with the control group, the expressions of DKK1 and ACTG2 were significantly downregulated while the expressions of JAK3 and SLC7A11 were significantly upregulated in the tissues of the sporotrichosis patients, consistent with the sequencing data." (PMID 38172590, 2024).
steatosis (1 paper, 2023). Increased lipid within the cytoplasm of cells. "Therefore, the causal relationship between DKK1 and steatosis is worth further investigation." (PMID 36410795, 2023). "Both HFD (first control) and HFD-AAV-GFP-NC (secondary control) revealed certain level of steatosis without significant difference; however, overexpressed DKK1 promoted the steatosis; furthermore, knock-down DKK1 significantly alleviated the steatosis under HFD condition." (PMID 36410795, 2023). "It suggests that the DKK1 promoted steatosis is CD36 dependent." (PMID 36410795, 2023). "Furthermore, those observations were confirmed by qPCR examination of steatosis-related genes in which the expressions of CD36 and PPARγ were significantly changed accordingly with the DKK1 manipulations under HFD." (PMID 36410795, 2023). "To delineate the pathologic role of DKK1 in steatosis, first, we found that the hepatic DKK1 expression status was progressively up-regulated as the NAFLD condition advanced in clinical patient and NAFLD mice liver samples and that was confirmed by in vitro fatty acid–induced hepatocyte steatosis." (PMID 36410795, 2023). "On the other hand, elevated DKK1 expression activates the JNK signaling pathway, which further inhibits AKT-FOXO1 phosphorylation cascades, promoting insulin resistance and glucose metabolism disturbances, thereby accelerating excessive lipid accumulation and steatosis." (PMID 36410795, 2023).
syndactyly (1 paper, 2019). A disease characterized by the presence of syndactyly, including syndromic and non-syndromic forms. "Mice lacking Dkk1 (dickkopf Wnt signaling pathway inhibitor 1) or Sfrp2 (secreted frizzled-related protein 2), genes encoding soluble inhibitors of Wnt signaling, develop syndactyly." (PMID 30679680, 2019).
Thrombocytopenia (1 paper, 2018). A reduction in the number of circulating thrombocytes. "Because thrombocytopenia is a feature of FA, we could argue against a role of platelets in DKK1 overproduction at least in these patients." (PMID 30028084, 2018).
Thrombocytosis (1 paper, 2018). Increased numbers of platelets in the peripheral blood. "Subsequently, the concentrations of Dkk‐1 calculated from the standard curve were normalized to platelet count, as platelets represent a major source for the circulating Dkk‐1,11 and MPN patients exhibit thrombocytosis." (PMID 29975001, 2018).
thymoma (1 paper, 2022). A neoplasm arising from the epithelial cells of the thymus. "SFRP2 and SFRP5 expression levels were increased in B2 thymomas, while AB thymomas showed increased DKK1 and DKK4 expression compared to other TETs and NTs." (PMID 35965500, 2022).
tumour syndrome (1 paper, 2009). "No relations of ASCL1/DKK1 expression to tumour syndrome, MEN 1, or WHO classification were observed." (PMID 19744316, 2009).
uremia (1 paper, 2018). A clinical syndrome associated with the retention of renal waste products or uremic toxins in the blood. "Interestingly, the increased circulating levels of the Wnt inhibitors sclerostin and Dkk1 have in uremia been suggested to be involved in the pathogenesis of the CKD-MBD, and a role of neutralizing antibodies against circulating Wnt-inhibitors has been proposed for treatment of CKD-MBD." (PMID 30075015, 2018).
Urethral stricture (1 paper, 2023). Narrowing of the urethra associated with inflammation or scar tissue. "We observed an overexpression of the Wnt proteins Wnt3a, β-catenin and also a significantly decreased expression of the the endogenous inhibitor DKK1 in human urethra tissues derived from patients with urethral stricture." (PMID 37859694, 2023). "We therefore performed rat model of urethral stricture and separated them into three groups: control groups, UF groups and UF treated with DKK1 groups (UF+DKK1)." (PMID 37859694, 2023).
uterine corpus endometrial carcinoma (1 paper, 2021). A endometrial carcinoma (disease) that involves the body of uterus. "The results demonstrated that DKK1 mRNA was overexpressed in a wide range of tumors (14 out of 27 types analyzed), such as esophageal, colon, stomach, and uterine corpus endometrial carcinoma, providing diverse research directions about the roles of DKK1 in tumors." (PMID 34093545, 2021).
uterine infection (1 paper, 2022). "When comparing all four studies, a total of 24 genes were consistently upregulated by pregnancy regardless of previous uterine infection, including DKK1, MX1, MX2, STAT1 and a number of interferon stimulated genes." (PMID 35358206, 2022).
uterine sarcoma (1 paper, 2021).
vitamin D insufficiency (1 paper, 2014). "We measured serum sclerostin and DKK1 in 34 patients (21 F, 13 M) aged mean (SD) 61.3 (15.6) years with vitamin D deficiency/insufficiency treated with a loading dose of vitamin D2 (300,000 IU) intramuscularly." (PMID 25548714, 2014). "The aim of this study was to determine changes in circulating concentrations of sclerostin and DKK1 following a loading dose of vitamin D2 (ergocalciferol) in subjects with vitamin D insufficiency." (PMID 25548714, 2014).
tumor (458 papers, 2007 to 2026). "Extrinsic immune suppression mechanisms: DKK1 shapes the immunosuppressive phenotype of tumor-associated macrophages (TAMs), limiting CD8+ T cell infiltration." (PMID 41050070, 2025). "It was proven that dysregulation of DKK1 and the Wnt pathway is linked to a wide range of diseases, including cancer, promoting tumor cell proliferation, migration, and metastasis." (PMID 40943055, 2025). "DKK1 has been implicated in inducing cancer stem cell transformation and modulating the immune environment to favor tumor progression by directly suppressing the activity of immune cells such as T lymphocytes." (PMID 40025612, 2025). "Humanized DKK1 mice (B-hDKK1) were used to evaluate the potential toxicity caused by TB643-070 upon administration since the antibody induced 13.78% tumor suppression and was developed from our internal machine learning model." (PMID 40394415, 2025). "Dysregulation of DKK1 can promote tumor growth and metastasis, with suppression linked to more aggressive cancer phenotypes." (PMID 40056285, 2025). "DKK1 was initially characterized as a tumor suppressor but has also been implicated in promoting tumor growth and metastasis." (PMID 39936971, 2025). "DKK1, as a critical component in the canonical Wnt pathway, is linked to a variety of GI cancers via its proapoptotic effect on tumor cells, leading to downregulation of β-catenin." (PMID 40943055, 2025). "Increased DKK1 expression has been linked to a more immunosuppressive tumor microenvironment (TME), which hampers immune surveillance and undermines the efficacy of ICIs." (PMID 41373587, 2025). "To further investigate the role of CAF-derived DKK1 during tumor progression, we co-injected Dkk1-deficient (Dkk1cKO) or sufficient (DkkWT) CAFs with PyMT tumor cells (1:1 ratio) into the MFP of naive WT recipient mice." (PMID 38659818, 2024). "For instance, it has been demonstrated that DKK1 is elevated in specific tumor tissues and is linked to clinicopathological variables, such as high tumor grade, lymph node metastasis, late N stage, and tumor-node-metastasis staging." (PMID 38376441, 2024). "Post-treatment, we observed that strong Dkk1 expression in primary tumours was associated with significantly worse ypT and ypN stages." (PMID 38254908, 2024). "Despite its role as a Wnt pathway antagonist, in certain contexts, elevated levels of DKK1 in CCA have been associated with tumor progression." (PMID 38730642, 2024). "High DKK1 expression was observed in 90% of cases in the more malignant poorly differentiated tumor, suggesting that DKK1 is associated with malignant progression of PDAC tumor." (PMID 39107271, 2024). "Highlighting the importance of local production of DKK1, mice co-injected with Dkk1 deficient CAFs showed smaller tumor size compared to mice co-injected with Dkk1 sufficient CAFs." (PMID 38659818, 2024). "In vivo, DKK1-SE deficiency not only inhibited tumor proliferation but also reduced the complexity of the tumor microenvironment." (PMID 39107271, 2024). "To better understand these associations, we examined how DKK1 expression varies across different tumor and normal tissues." (PMID 38376441, 2024). "Dkk1 expression in primary BC tumours was associated with increased cT stage, positive ER and PR expression, lower G stage, and lower Ki-67 index." (PMID 38254908, 2024). "DKK1 was found to be associated with tumour size, liver dysfunction, and poor performance status in HCC patients." (PMID 36901717, 2023). "Several studies have shown that DKK1 is an oncogene in cancers, and its aberrant expression is associated with tumor progression and poor prognosis." (PMID 37835450, 2023). "Dickkopf-1 (DKK1) is upregulated in many types of cancer, and its inhibition has been associated with decreased tumor proliferation, migration, and invasion in preclinical trials." (PMID 37190050, 2023).
tumor (continued). "In parallel, DKK1 and β-catenin expressions detected using IHC staining were associated with tumor size, N staging and tumour stage." (PMID 35907982, 2022). "Univariate analysis indicated that hepatic reserves (Child–Pugh classes and ALBI grades), tumor stages (UICC and BCLC stages), and tumor markers (DKK-1, AFP, and PIVKA-II levels) were risk factors for poor survival outcomes." (PMID 35269944, 2022). "In the present study, we have assessed the association of serum DKK-1 levels with patient and tumor characteristics as well as with response to TACE and survival after TACE in a European population with HCC for the first time." (PMID 36230730, 2022). "We aimed to investigate the association of serum DKK-1 levels with tumor and patient characteristics in a European population and to characterize its role as a biomarker for TACE treatment outcomes." (PMID 36230730, 2022). "A study of tumor tissue samples from 205 lung cancer patients showed that DKK1 expression was positively linked with vasculogenic mimicry, which led to greater invasiveness of cancer cells." (PMID 35355709, 2022). "Osteolysis, a hallmark of MM and a severe complication seen in nearly 80% of cases, is strongly linked to the secretion of DKK1 by MM tumor cells." (PMID 35881476, 2022). "The risk heatmap indicates that TRIML2, CAMK2N1, and DKK1 were upregulated in the high-risk cluster, suggesting their tumor-promoting role." (PMID 36685979, 2022). "Increased circulating DKK1 levels in cancer derive from both the tumor as well as the host and are frequently associated with a poor prognosis." (PMID 36539532, 2022). "Although Dkk-1 functions as a naturally occurring negative regulator of Wnt signaling, Dkk-1 expression is often associated with poor prognosis in gastrointestinal cancers, and Dkk-1 blocking antibodies can inhibit tumor growth in pre-clinical animal models." (PMID 35358569, 2022). "Additional studies are required to determine the potential associations of DKK1 expression in blood and tumor tissues with disease outcome." (PMID 34974279, 2022). "In our study, we found that the DKK1 expression was significantly upregulated in tumor tissues and was significantly associated with overall survival." (PMID 33969120, 2021). "Based on the ability of DKK1 to inhibit the Wnt pathway, DKK1 was initially characterized as a tumor suppressor, but many studies have now linked DKK1 to cancer promotion." (PMID 34117362, 2021). "DKK1 expression is elevated in a range of tumor types and this is frequently associated with a poor clinical prognosis." (PMID 33972574, 2021). "In HCC, DKK-1 was shown to be abnormally overexpressed in tumor tissues or serum and was associated with multiple metastatic lymph nodes, vein infiltration, and the diagnosis of HCC." (PMID 34123800, 2021). "Patients with high S100A4 and low DKK1 expression levels in the primary tumor can be classified as high risk for OS." (PMID 35008201, 2021). "Meanwhile, the results from western blots showed that the high expression of Dkk-1 was observed in the primary tumor tissues and the associated precancerous lesions, while the neighboring lung tissues showed the low expression of Dkk-1." (PMID 33384994, 2020). "The reduced tumor growth upon EHMT2 deficiency was reversed by recombinant DKK1 or LGK974, which also inhibits Wnt signaling." (PMID 33252038, 2020). "In these patients, the association between higher tumour expression of DKK1 and better survival outcome was stronger (NKI; p = 0.005." (PMID 31676788, 2019). "A recent study reported that carbonic anhydrase IX (CA9), which modulates tumor-associated cell migration and invasion, interacts with DKK-1." (PMID 28938611, 2017). "The aim of this study was to examine the diagnostic value of DKK1, correlating its serological levels with tumor stage and survival rate in PC patients." (PMID 26101916, 2015).
tumor (continued). "Elevated DKK1 level significantly correlated with positive β-catenin accumulation, and they were remarkably associated with histological grade and Musculoskeletal Tumor Society stage." (PMID 25144498, 2014). "Studies have shown that blocking DKK-1 and activating Wnt signaling prevent bone disease in MM but are also associated with a reduction in tumor burden." (PMID 23818912, 2013). "DKK1, encoding a secreted protein, is an antagonist of the Wnt/β-catenin signaling that is involved in tumor progression." (PMID 24391982, 2013). "The expression of DKK1 was found associated with the lymph node status, tumor stage and the expression of beta-catenin was associated with pathology type." (PMID 22649545, 2012). "Multivariate analysis indicated DKK1 to be an independent risk factor for relapse free survival and tumor stage to be an independent risk factor for overall survival." (PMID 22649545, 2012). "Kendall's tau-c association analysis also revealed the increased DKK-1 protein expression in tumor tissues of higher pathologic classification." (PMID 21029453, 2010). "Kendall's tau-c association analysis also revealed the increased DKK-1 protein expression in tumor tissues of higher pathologic classification (rτ = 0.3178, P < 0.01)." (PMID 21029453, 2010). "However, DKK1 has also been linked to the promotion of cancer, and the ability of DKK1 to function as a tumor suppressor or promoter depends on numerous factors including the type of cancer, heterogeneity within the tumor, and tumor microenvironment." (PMID 40001961, 2025). "Although the precise underlying mechanism remains unclear, it is speculated that DKK1 contributes to tumor immune evasion." (PMID 38886806, 2024). "Furthermore, DKK1 expression was linked to nodal metastatic status, tumor grade, individual cancer stage, and presence of HPV in HNSCC." (PMID 38376441, 2024). "Dickkopf-1 (DKK1), a secreted regulator of the Wnt signaling pathway, is overexpressed in a variety of cancers and has been associated with tumor immunosuppression, and DKN-01 can act by blocking DKK1 and in so doing enhances the innate immune response of tumors." (PMID 38634048, 2024). "Importantly, we identify neomorphic antiestrogenic activities through the downregulation of DKK1, a tumor-secreted glycoprotein that is associated with metastasis in other cancers." (PMID 38978585, 2024). "However, by altering the tumour microenvironment and causing inflammation, DKK1 seems to promote tumour invasion and migration via TGF-β1." (PMID 36901717, 2023). "DKK1 is closely associated with tumor immune cell infiltration and pathways." (PMID 37752538, 2023). "Dickkopf-1 protein (DKK1) is an antagonist of the Wnt signaling pathway, and overexpression of DKK1 has been associated with tumor growth, angiogenesis, and a more immunosuppressive tumor microenvironment." (PMID 37238666, 2023). "The tumor suppressive activity of FoxA2 is associated with its induction of Dkk1, Cu12 and Cdc73." (PMID 37298091, 2023). "It is unclear whether DKK-1 levels show a similar association in European patients that have a different genetic and different tumor etiology." (PMID 36230730, 2022). "Anti-DKK1 antibody resulted in diminished tumor growth and prevented bone loss." (PMID 34093545, 2021). "Moreover, many of the studies we included not only used BKK-1 as a tumour biomarker but also explored the diagnostic synergistic effects of DKK-1 and other markers, including the combination of AFP in HCC and the combination of CA19-9 in PC." (PMID 33193872, 2020). "Interestingly, while DKK1 was thought to be tumor suppressive in nature, it is now found to be associated with poor prognosis, supporting tumor growth and metastasis." (PMID 31167446, 2019). "Consistent with previous reports that DKK1 might be implicated in tumor development and progression, our study showed that DKK1 expression was low in primary TSCC tissues and was inversely correlated with miR-373-3p levels." (PMID 28337453, 2017).